GFAP (glial fibrillary acidic protein)
Diseases named in the same sentence as GFAP in open-access papers (continued):
Sharing a sentence is not in itself a finding about the gene and the disease.
glioma (continued). "Instead, van Bodegraven and coworkers proposed that astrocytoma malignancy is well reflected by the ratio of GFAP isoforms GFAPδ and GFAPα (a canonical GFAP isoform), which could improve the accuracy of assessing the differentiation state of this type of glioma." (PMID 32630739, 2020). "Some of these cells may be glioma stem-like cells that lost GFAP expression." (PMID 32349320, 2020). "Glioma cell treatment with N6,2′-O-dibutyryl cAMP (Bt2AMP) and theophylline caused delayed phosphorylation of the signal transducer and the activator of transcription-3 (STAT3) as well as expression of an astrocyte marker, glial fibrillary acidic protein (GFAP)." (PMID 31500285, 2019). "Possibly, there is a specific subpopulation of GFAP expressing cells in grade IV glioma that is well‐equipped to enter the bloodstream and GFAP isoform expression might be used to further characterize this subpopulation of cells that are associated with a higher malignant astrocytoma." (PMID 30667110, 2019). "Interestingly, two genes involved in cytoskeleton and cell shape are downregulated by DHO-specific mutations and represent useful biomarkers: Glial Fibrillary Acidic Protein (GFAP), an astrocytic biomarker more highly expressed in IDH-A than in IDH-O gliomas and RhoC Guanosine Triphosphate (RHOC)." (PMID 30279357, 2018). "However, in combination with survivin expression, and viewed within the right clinical context, GFAP may add to the specificity of detection of glioma-derived serum exosomes." (PMID 29383115, 2017). "The metabolic profiles from cell lines might provide information associated with their malignant features and other biological features; therefore, we further investigated the correlation of these characteristic metabolites with the glioma malignant behavior markers GFAP and MMP-9." (PMID 25163530, 2014). "In addition, GFAP-Cre lines have been used to generate murine glioma models due to conditional deletion of tumor suppressor genes and astrocytomas form with high penetrance in mice in which activated Ras is expressed from the GFAP promoter." (PMID 25423036, 2014). "Moreover, GFAP was identified as a tumor suppressor gene in astrocytoma and glioma pathogenesis." (PMID 23601182, 2013). "Additionally, in a cell line (Ric0) derived from resected gliomas from newborn GFAP-Cre/RictorloxP/loxP mice expressed the Rictor transgene, stained positive for GalC and demonstrated hyperactivation of mTORC2 as compared to oligodendrocytes isolated from control littermates." (PMID 23077666, 2012). "Large numbers of nestin-positive host cells were found at the immediate tumor border, whereas GFAP-positive host cells with typical astrocytic morphology were distributed loosely in a halo more distal to the zone containing mouse nestin-positive cells that surrounded the D566 human glioma implants." (PMID 22539956, 2012). "At 12 weeks highly invasive GFAP-/Nestin + high-grade astrocytomas develop, a progression that is accompanied by additional changes including overexpression of EGR, MDMT, loss of Pten and p16 and p19, all of which are known genetic markers associated with malignant human gliomas." (PMID 21896959, 2011). "After addition of DSA to glioma cells, the cells grew at a much reduced rate, they changed from a flattened epithelioidal shape to a stellate shape having two or more long processes, so that some of the cells resembled normal fibrous astrocytes, and their content of GFAP was strikingly increased." (PMID 12373609, 2002). "Co-staining with glial fibrillary acidic protein (GFAP; glioma) or pan-cytokeratin (BrM) membrane markers revealed diverse localization patterns of bacterial 16S rRNA, including cytoplasmic, membrane-adjacent and extracellular distributions." (PMID 41238915, 2025). "qPCR analysis of 38 genes was investigated, including the glioma cell marker, GFAP; prognostic glioma classification markers, IDH1/2; and glioma cell stemness markers, NANOG, SOX2, SOX2-OT and CD133." (PMID 41034696, 2025).
glioma (continued). "GBM RNA transcriptome datasets were used to examine the expression levels of GFAP, AQP4, and PLEC in healthy tissue versus glioma; samples were obtained from 28 healthy human controls (HCs), 148 patients with astrocytoma, and 221 patients with GBM." (PMID 38263015, 2024). "CB1R appears to be primarily expressed on glioma cells, in contrast to CB2R, as indicated by its colocalization with the astrocytic marker glial fibrillary acidic protein (GFAP)." (PMID 38720772, 2024). "Higher magnification images confirmed that tdTOM mostly colocalized with either GFAP or SOX10, indicating that they are “mixed gliomas” comprising of both astroglial or oligodendroglial lineages, respectively." (PMID 39609428, 2024). "Histologically, in GFAP-Cre PDGFA transgenic mice, spontaneous gliomas exhibited characteristics of both astrocytes and oligodendrocytes and were classified as WHO grade III oligoastrocytomas." (PMID 38473403, 2024). "Amongst GFAP-expressing cells, we observed a ~30% increase in the fraction that were vimentin-positive (p = 0.036, 2-tailed paired t-test, n = 3 tissue samples from different patients), suggesting that even in low-grade gliomas, a vast majority of tumor cells may be aggressive." (PMID 38295184, 2024). "The GFAP-Cre; KrasG12D; APCL/+; p53L/L mice displayed many significant features of human gliomas, including more giant cell formation, hemorrhage, increased cellularity, vascular proliferation, and necrosis, which lead to classification as a grade IV glioma." (PMID 38473403, 2024). "Similar to control tumors, Ascl1-OE GFP+ tumor cells co-localized with either GFAP or SOX10, indicating a “mixed glioma” phenotype." (PMID 39609428, 2024). "We first performed antigen retrieval and stained high-grade glioma and normal hippocampus with anti-vimentin or anti-MAP/anti-GFAP." (PMID 38295184, 2024). "Multiplexed fluorescence immunohistochemistry staining of PDPN, GFAP, CD68, and CD163 were performed in glioma tissue microarray." (PMID 38470096, 2024). "Gliomasphere line specific (EGFR) and cell cycle markers (MKI67, TOP2A) dominated clustering and we noted enrichment of glioma stem cell (PTPRZ1, SOX2) and astrocytic markers (GFAP, S100B) in GS025." (PMID 38856710, 2024). "The combination of two markers (GFAP and FABP4) further enhances the discrimination between gliomas and meningiomas." (PMID 38879494, 2024). "While 15/16 control animals in which DN-ATF5 was turned off at the time of tumor induction developed tumors that expressed GFAP and ATF5, only 1/7 animals in which DN-ATF5 was on at the time of tumor induction developed a glioma." (PMID 36831248, 2023). "The CSCs of paediatric high-grade gliomas were isolated as early as 2003, with stemness markers of Nestin and Musashi, along with the differentiation markers of Beta-III Tubulin, GFAP, and Oligodendrocyte Marker O4." (PMID 37370764, 2023). "A recent study demonstrated that two proteins, chitinase-3-like protein 1 (CHI3L1) and glial fibrillary acidic protein (GFAP), to be a potential CSF Biomarkers for glioma patients." (PMID 37633929, 2023). "An interesting future experiment to further determine the expression patterns in different cell types of glioma tissue would be double fluorescence staining with BRMS1 and cell-type-specific markers, such as IDH1R132H, NeuN, GFAP, or CD68." (PMID 37296870, 2023). "Expression of innate and other adaptive immune genes, including GFAP for activated astrocytes and IBA-1 for microgliosis, were comparable between IDH1R132H and IDH1-wild-type gliomas." (PMID 37161052, 2023).
glioma (continued). "In a recently described extremely rare epileptogenic angiocentric glioma, there are high levels of vimentin expression, epithelial membrane antigen (EMA) and glial fibrillary acidic protein (GFAP)." (PMID 38067243, 2023). "We identified 8 plasma proteins which were increased in gliomas vs. meningiomas (GFAP, NEFL, EDDM3B, PROK1, MMP3, CTRL, GP2, SPINT3) and 4 proteins which were decreased in gliomas vs. meningiomas (FABP4, ALDH3A1, IL-12B and OXT)." (PMID 36959545, 2023). "Specifically, the nature of the interaction between GFAP and FABP4 and its role in glioma diagnosis and prognosis requires further study." (PMID 36959545, 2023). "The use of a tumour-specific promoter, Glial fibrillary acidic protein (GFAP), has previously been described in a HAdV-C5 background and demonstrated selectivity towards glial tumours." (PMID 37243172, 2023). "In particular, the panel included extracellular and intracellular antigens expressed on normal brain and tumor cells (e.g. GFAP, CD140α, CD90), stem cells and glioma cancer stem cells (e.g. Nestin, Musashi-1, CD34)." (PMID 36568177, 2022). "We measured average quantities of GFAP per cell experimentally and found, in line with these previous studies, that it was more variable in GBM cells compared to glioma stem cells." (PMID 35919979, 2022). "As hsa_circ_0008922 was up-regulated in gliomas, we further investigated the correlation between the expression of hsa_circ_0008922 and clinical data such as age, gender, tumor size, WHO grade and GFAP (glial fibrillary acidic protein)." (PMID 36570001, 2022). "GFAP protein-expressing neural stem cells (NSCs) are responsible for the activation of PDGF receptors and their stimulation, which eventually form the glioma-like mass." (PMID 35327982, 2022). "The markers were glioma stem cell markers (CD133 and Msh1), neuronal lineage markers (nestin, sox1, sox2, and pax6), and differentiated markers (GFAP, Tuj1, and Olig123)." (PMID 33575478, 2021). "The level of expression glioma-characteristic genes (e.g. CD34, GFAP, OLIG2, MAP2, MKI67, RBFOX3, SOX2, SYN; Suppl." (PMID 34545083, 2021). "The glial fibrillary acidic protein (GFAP) and oligodendrocyte lineage transcription factor 2 (OLIG2) are two such examples of glioma markers routinely assessed by IHC during diagnosis." (PMID 33673213, 2021). "Western blotting and immunostaining showed increase in molecular markers (GFAP, NeuF-H, β-tubulin-III, MAP2, Nestin, and GAP43) that confirmed the differentiation of glioma to astrocytes." (PMID 35011307, 2021). "The genes AQP4, BCAN, GFAP, PLP1, and S100B are part of the astrocytic, oligodendrocytic, or proneural glioma signatures." (PMID 34101353, 2021). "In human gliomas, expression of CSF1 is present in glial fibrillary acidic protein (GFAP)-positive cells." (PMID 34063518, 2021). "The particular combination of glial (GFAP) and vascular (SMA) markers was also observed for gliosarcomas, a subtype of gliomas." (PMID 34359860, 2021). "To examine the presence of astrocytes in hypoxic areas in vivo, we stained whole brain sections from glioma-bearing mice for HIF-2α (to mark the hypoxic areas) and GFAP (to mark the activated astrocytes)." (PMID 33802060, 2021). "Within the field of glioma biology, PAX3 has been established as a regulator of GSCs through its modulation of glial fibrillary acidic protein (GFAP) expression." (PMID 34012965, 2021). "We also observed an interesting phenomenon: GFAP and AQP4 expression in the internal core and periphery of glioma differed, where the peripheral area was significantly enriched with GFAP and AQP4." (PMID 35083148, 2021). "Our results demonstrate brain tissue-specific proteins such as GFAP and PLP1 to be present in both TiMas and subsets of blood monocytes, especially in diseases with brain tissue-damage such as glioma, brain metastases and AIS." (PMID 33501422, 2021).
glioma (continued). "GFAP+CD16+ monocyte relative numbers were evaluated for their relationship with OS and progression-free survival in glioma patients." (PMID 33501422, 2021). "The functionality of the cells in the tumor model was evaluated by the expression of the glial fibrillary acidic protein (GFAP) receptor, a specific marker for astrocytes and glioma cells." (PMID 32365781, 2020). "SPIONs drive miR-485-5p overexpression in cells and inhibit endogenous Tie1 expression to downregulate the protein expression levels of Fgf2/GDNF/GFAP/BDNF and significantly weaken the in vivo and in vitro viability of gliomas." (PMID 32174801, 2020). "Recently, it has been reported that strong expression of glial markers, including GFAP, S100β, and OLIG2, and elevated p-ERK levels are observed in the glioneuronal tumors or glioma of NS patients." (PMID 32493428, 2020). "Remarkably, we observed that about 50% of cells differentiated into astrocytes with glioma features as demonstrated by the co-expression of CD133 and GFAP." (PMID 32649728, 2020). "Immunofluorescent staining showed increased expression of Tuj1 and GFAP both in the U87MG and M059J glioma cells after CA treatment (25 or 50 μM, 24 h) indicating the shift toward neurological characteristics." (PMID 31660066, 2019). "Recent studies reported that glioma cells expressing lineage markers such as A2B5, NG2, CD44, and even GFAP also meet the criteria for tumorigenic stem cells, suggesting that GIC originate from a broader spectrum of neural lineages." (PMID 31618934, 2019). "In order to explore the distribution of CYP2B1 in the brain tissue of animals with glioma, we performed an immunofluorescence for the CYP2B1 protein (red) and glial fibrillary acidic protein (GFAP; green)." (PMID 29914177, 2018). "The immunohistochemical expression of glial cell markers, such as glial fibrillary acidic protein or oligodendrocyte transcription factor (OLIG2), suggests a glial tumor." (PMID 29881714, 2018). "In the glioma patients, a relatively large fraction (range 18.2 – 27.1%; mean = 22.8%) of CD9+ exosomes had GFAP on their surface." (PMID 29383115, 2017). "Serum from glioma patients contained abundant CD9+ exosomes with both SVN and glial fibrillary acidic protein (GFAP) on their surface." (PMID 29383115, 2017). "Vascular Endothelial Growth Factor-A (VEGF-A), GFAP and muscle-specific pyruvate kinase-M2 (PKM2) are upregulated in glioma, and the level of upregulation of VEGF, VEGF receptor 2 (VEGFR2), GFAP, and PKM2 correlate with tumor grade and lethality (review)." (PMID 26689994, 2016). "To test this we performed qPCR on a selected panel of mRNAs of importance in glioma stem cell function: CD133, nestin, vimentin, TUJ1, GFAP and MAP2." (PMID 27564115, 2016). "Three slides, bearing 20 GBM, 7 lower grade glioma and control human temporal brain tissue, were simultaneously prepared for MAOB, HiF-1α, GFAP immunohistochemical labeling/staining and were imaged in a single session, using identical microscope settings." (PMID 26689994, 2016). "Immunofluorescence staining of glioma cells (60th generation), assessed by laser confocal microscopy, revealed the presence of IDH1R132H, A2B5, GalC, Vimentin, GFAP, and S-100 (B1-B6)." (PMID 25879429, 2015). "An increase of circulating GFAP levels was observed in pre-operatively collected samples from grade III and IV glioma patients in both serum and plasma." (PMID 25720744, 2015). "Major discriminator between high-grade and low-grade tumors included CRYAB, IPYR, TPIS, PEA15, PSD13, GFAP, IDH3A, 6PGL, PHP14, KCRB as overexpressed in low-grade gliomas; HCD2, HBA, HBD as overexpressed in high-grade GBM." (PMID 25050814, 2014).
glioma (continued). "It is noteworthy that the GB-749 glioblastoma hybrid tumor showed retention of glioma-related genes (PLAGL2, GFAP), whereas the lymphoma-derived hybrid tumor retained several B-cell antigen receptor (BCR)-related genes (CD19, CD20, CD71, CD79b)." (PMID 25259521, 2014). "The comprehensive analyses of GFAP and MMP-9 expression levels, and invasion ability indicated that the cell lines from glioma tissues of different pathological grades showed obvious variations in malignant behavior." (PMID 25163530, 2014). "In these PDGF-driven gliomas, PDGF-GFP infected tumor cells and GFAP-expressing astrocytes were expressed in mutually exclusive areas, confirming that the astrocytes in our tumors are stromal." (PMID 22393407, 2012). "The similarities between GFAP+NNP cells and a subpopulation of glioblastoma cells isolated from high-grade gliomas presented in this study shed new light on glioblastoma biology." (PMID 19216795, 2009). "The depletion of microglia in a glioma model in human brain slices resulted in a significant decrease in the activity of the astrocyte JAK/STAT signaling pathway, which was accompanied by a downregulation of GFAP and CD274 expression." (PMID 40243478, 2025). "Costaining revealed elevated GFAP+-SLC31A1+, GFAP+-FDX1+, GFAP+-DLAT+, and GFAP+-DLST+ astrocytes in DSF-treated ECM mice, consistent with reports linking copper overload (e.g., via FDX1/SLC31A1 upregulation) to glioma progression and copper/zinc ionophores (e.g., CPT/ZPT) to astrocyte toxicity." (PMID 41214704, 2025). "Furthermore, double-labeling experiments with GFAP, a well-established astrocytic and glioma marker in rodent models, revealed substantial co-localization of BBG with GFAP-positive tumor cells." (PMID 41226489, 2025). "It is known that in GBM patients (GBMPs), unlike patients with other types of malignant tumors of the central nervous system, the concentration of one of the cytoskeleton proteins—glial fibrillary acidic protein (GFAP)—is increased in the blood." (PMID 39996852, 2025). "There is a lack of accurate knowledge about the effects of PDT on some molecules that are important for the effectiveness of glioma therapy, such as transforming growth factor β (TGF-β), and the information on some of them (e.g., HGF, HDACs, GFAP, and others) is far from sufficient." (PMID 39201395, 2024). "In addition, both DM-α-KG and SP promoted the differentiation of glioma cells through elevated GFAP expression and reduced Nestin, CD133, and CD44 expression, suggesting that α-KG accumulation can promote the differentiation of glioma cells." (PMID 39872214, 2024). "Nonetheless, GFAP expression is not ubiquitous across all glioma cells and therefore is not an ideal biomarker for glioma diagnosis." (PMID 39062515, 2024). "A stereotactic brain biopsy and subsequent neuropathological evaluations were performed, resulting in a glioma tumor isocitrate dehydrogenase 1 (IDH-1) and 2 (IDH-2) wild type, glial fibrillary acidic protein (GFAP) and oligodendrocyte transcription factor 2 (Olig2) positive." (PMID 37692853, 2023). "Tumors stained mostly negative for glial histological markers commonly used for gliomas, such as GFAP and Olig2." (PMID 36869047, 2023). "The choice of specific antibodies to GFAP proved crucial, as non-specific IgG exhibited minimal or no accumulation even in a glioma model with compromised BBB function." (PMID 37628867, 2023). "ZDHHC5-mediated palmitoylation of EZH2 activates histone H3 Lysine 27 trimethylation (H3K27me3), suppresses miR-1275, elevates Glial Fibrillary Acidic Protein (GFAP) expression, and decreases DNA methyltransferase 3 alpha (DNMT3A) binding to the OCT4 promoter, contributing to glioma malignancy." (PMID 38067206, 2023). "GFAP mRNA in the RG-2 glioma cells in culture was not detectable by Northern blotting even after over-exposure of the film." (PMID 35745855, 2022).